PPARG (peroxisome proliferator activated receptor gamma)
Diseases named in the same sentence as PPARG in open-access papers (continued):
Sharing a sentence is not in itself a finding about the gene and the disease.
asthma (87 papers, 2005 to 2025). "Activation of PPARγ has been shown to downregulate pro-inflammatory cytokines and decrease airway hyperresponsiveness, a hallmark of asthma." (PMID 41149648, 2025). "Pretreatment of ACC1-deficient invariant natural-killer T (iNKT) cells with PPARγ agonist or exogenous fatty acid restores ovalbumin (OVA)-induced asthma." (PMID 37917548, 2023). "Genetic variants or single nucleotide polymorphisms (SNPs) in PPARG and oxidative stress-related genes have been associated with increased risk of asthma development and exacerbations, highlighting gene-environment interactions in asthma pathophysiology." (PMID 36114491, 2022). "Another evidence supporting EP4 signal was essential in asthma came from our data that PGE2 and PPARγ are closely linked in the context of B cell differentiation and asthma." (PMID 32636842, 2020). "The correlation between PPARγ polymorphism with the increased risk of asthma in humans indicates that the role of PPARγ in anti-inflammatory reaction occurs at the gene expression level." (PMID 30400642, 2018). "PPARγ has been proposed to be closely involved in regulating the inflammatory states underlying many airway diseases and PPARγ agonists have been suggested as alternative anti-inflammatory therapeutics in asthma." (PMID 21897859, 2011). "Downregulation of PPARγ causes lipid-rich alveolar mesenchymal fibroblasts to transdifferentiate into myofibroblasts, which is the cellular hallmark of chronic lung diseases such as asthma." (PMID 36359869, 2022). "In one study of Koreans, the PPARG polymorphism rs3856806 was associated with asthma development." (PMID 36114491, 2022). "The largest numbers of studies have been carried out on ADRB2 and PPARG, but the fact that they also have reported associations with asthma and T2D, respectively, may account for this." (PMID 24410812, 2014). "Although PPARγ was originally characterised as a regulator of adipocyte differentiation, this receptor is also widely expressed in the lung, in both inflammatory and structural cells implicated in asthma pathophysiology." (PMID 22966222, 2012). "Furthermore, it opens doors for exploring PPARγ as a potential therapeutic target for interventions aimed at modulating senescence-associated processes in ACO–a condition marked by mixed features of both asthma and COPD, known for its increased severity." (PMID 38643159, 2024). "Furthermore, polymorphism of the PPARG gene may be related to an increased risk of asthma development." (PMID 33362766, 2020). "Qiang Xiao and others identified PPARγ as a key regulator of ILC2 in the lungs, which provides a renewed perspective on the effect of PPARγ in asthma." (PMID 39800672, 2025). "The PPARγ agonist rosiglitazone has been shown to decrease airway inflammation and remodeling in murine models of asthma by activating the PPARγ/HO-1 signaling pathway." (PMID 41149648, 2025). "PPARγ, which has been extensively studied in the field of lipid metabolism and insulin signaling, also plays a crucial role in allergic diseases such as asthma." (PMID 38030614, 2023). "The significant increase in M2 macrophages in the airways of asthmatic patients compared to healthy controls also suggests a potential role for PPARγ in asthma and in allergic inflammation." (PMID 38030614, 2023). "In conclusion, macrophage NCOR1 deficiency promoted the regulation of M2 programming by enhancing PPARγ expression to exacerbate asthma." (PMID 38030614, 2023). "Mechanistic studies suggested that NCOR1 promoted macrophage polarization by interacting with PPARγ, contributing to the pathogenesis of asthma." (PMID 38030614, 2023). "Single nucleotide polymorphisms (SNPs) of peroxisome proliferator-activated receptor gamma (PPAR-γ; gene: PPARG) and oxidative stress genes are associated with asthma risk." (PMID 36114491, 2022). "In this study, we constructed the PPI network; IL6, CASP3, EGFR, MAPK8, ESR1, CCND1, and PPARG were found to be the core genes of YPF in treating asthma." (PMID 36105239, 2022).
asthma (continued). "Rosiglitazone is a PPARγ agonist that has shown a beneficial effect in both mice and humans with asthma." (PMID 35600600, 2022). "And on the other hand, the deletion of PPARγ in lung DCs protects from HDM-induced asthma development, by reducing their migration to the draining lymph nodes, pointing towards a pro-inflammatory role of this nuclear receptor." (PMID 34012456, 2021). "Regarding the significance of ADPN modulation of PPARs in asthma, it is notable that PPARα and PPARγ expressions are upregulated in the lung tissue of OVA-challenged obese mice." (PMID 34445677, 2021). "alleviated ovalbumin-induced asthma in mice in a fashion dependent on the upregulation of the PPARγ gene and blocking protein kinase B (PKB or Akt) and phosphatase and tensin homolog (PTEN) phosphorylation." (PMID 33467433, 2021). "Asthma development implicates PPARG in regard to the reduction of respiratory inflammation and the permanent remodeling that occurs due to the chronic asthma response." (PMID 32185106, 2020). "Meanwhile, in vivo asthma model, the PPARγ antagonist T0070907 was found to boost serum IgE and OVA-specific IgE levels in OVA-induced mice, as well as higher inflammatory infiltration." (PMID 32636842, 2020). "In N-ERD vs. asthma comparison, we detected five SNPs in four genes (PPARG, IL10, PTGER2, and OBSCN)." (PMID 31936183, 2020). "PPARγ activation improves airway remodeling and airway smooth muscle cell contractility in asthma models." (PMID 33082140, 2020). "It is also reported that administration of PPARγ agonists or overexpression through adeno-PPARγ provides protection against asthma in mice." (PMID 33574813, 2020). "Each of the five identified target proteins, ESR1, KDR, LTA4H, PDE4D and PPARG, have established potential to play significant roles involving both the primary and secondary asthma pathways through many signaling cascade pathways." (PMID 32185106, 2020). "Currently, PPARγ is thought to be expressed in the lung and in a murine model of asthma, and treatment with a PPAR-γ agonist can inhibit the development of allergic inflammation, including pulmonary eosinophilia and airway AHR." (PMID 32636842, 2020). "In a murine asthma model, the use of PPARγ agonists can alleviate airway hyperresponsiveness to inhibit the development of allergic inflammation." (PMID 32636842, 2020). "Application of NeTFactor to a multi-gene expression-based asthma biomarker identified ETS translocation variant 4 (ETV4) and peroxisome proliferator-activated receptor gamma (PPARG) as the biomarker’s most significant TF regulators." (PMID 31506535, 2019). "Just these two TFs regulated 24 (27%) of the asthma biomarker genes, including SERPINE237 and CDHR338, asthma-associated genes co-regulated by ETV4 and PPARG." (PMID 31506535, 2019). "Then, our current study further explored the underlying mechanism of curcumin in suppressing airway inflammation in asthma, accumulating more evidence of the role of PPARγ in the pathogenesis of asthma." (PMID 31073274, 2019). "The peroxisome proliferator activated receptor γ (PPARγ) is an emerging anti-inflammatory, anti-oxidative protein and plays an important role in a variety of lung diseases such as asthma and COPD." (PMID 30212482, 2018). "Peroxisome proliferator-activated receptor gamma (PPAR-γ) is a nuclear receptor that modulates inflammation in models of asthma." (PMID 27560168, 2016). "Recently, the studies have shown increased PPARγ expression in the bronchial epithelial cells of asthma patients, but decreased PPARγ expression in allergic inflammation and acute lung injury induced by LPS." (PMID 24612634, 2014). "PPARγ is important in the control of asthma, allergy, and airway inflammatory responses and the modulation of allergic inflammation through up-regulation of PTEN (phosphatase and tensin homolog)." (PMID 23469025, 2013).
asthma (continued). "ASM PPARγ expression is increased in bronchial biopsies from people with asthma and thiazolidinediones reduce airway hyperreponsiveness in animal models of allergic airways disease." (PMID 23034049, 2012). "In contrast, perinatal exposure to nicotine appears to decrease PPARγ expression and signaling, with increased alveolar interstitial fibroblast-to-myofibroblast differentiation contributing to the development of an asthma-like phenotype in newborn rats." (PMID 22966222, 2012). "A potential novel approach to regulate ASM function in asthma is to target peroxisome proliferator-activated receptor γ (PPARγ)." (PMID 22966222, 2012). "Previous studies about the potent anti-inflammatory properties of the PPARG agonists suggest the use of PPARG ligands in COPD therapy and association of PPARG gene polymorphisms with the development of asthma has been reported." (PMID 21044285, 2010). "PPARγ agonists also reduce the clinical symptoms in animal models of asthma, a disease which is also thought to be predominantly Th2 type involving IL4, IL5, and IL13." (PMID 17207275, 2007). "A role for PPARγ in allergic conditions as well as asthma has been suggested, but remains controversial." (PMID 16271155, 2005). "In murine models of human asthma, it has been demonstrated that local administration of PPARγ agonists decreases serum levels of IgE, and have beneficial effects on airway hyperresponsiveness and lung eosinophilia." (PMID 16271155, 2005). "Similar in vivo findings have been seen in a murine model of asthma, where treatment with a PPARγ agonist inhibited the development of allergic inflammation, including pulmonary eosinophilia and airway hyperreactivity." (PMID 16271155, 2005). "Furthermore, systemic treatment with a pharmacological PPARγ agonist has shown to reduce inflammation, partly by inhibiting DC function in various inflammatory diseases, including asthma." (PMID 38521900, 2024). "Moreover, PPARG also reduces the morbidity in the experimental models of asthma, COPD and acute lung injury." (PMID 38750544, 2024). "PPARγ agonist (rosiglitazone) can effectively block asthma induced by perinatal smoke exposure." (PMID 36359869, 2022). "A previous study has shown that PPARG modulates inflammation and may have an effect on regulating the long-term control of asthma in children and young adults." (PMID 34456632, 2021). "This might be the reason why lobeglitazone, which has the benefits of activating both PPARα and PPARγ, had such extensive effects on asthma (reduction in inflammatory infiltrate, hyperresponsiveness, mucus secretion)." (PMID 34445677, 2021). "However, the proposed beneficial role of PPARs in asthma was brought into question by the recent finding that IgE promotes airway inflammatory remodelling in asthma patients by activating the PPARγ pathway." (PMID 34638914, 2021). "PPARγ has been considered a molecular target for effective asthma therapy." (PMID 33467433, 2021). "However, interpretation of PPARγ level in asthma requires particulars, because this parameter can change depending on the stage of inflammation (initiation or resolution)." (PMID 32395125, 2020). "Thus, rigorous studies and clinical research are required where a larger sample size and distinct endotypes are considered in order to translate PPARγ agonists into asthma drugs." (PMID 33574813, 2020). "Furthermore, a current review of rosiglitazone defines the PPARG agonist as a key regulator of airway inflammation, with strong evidence as an asthma therapeutic target." (PMID 32185106, 2020). "Given PPARγ agonists have been reported to treat inflammatory lung disease, EP4 regulation combined with PPARγ may present a potential therapeutic strategy for asthma in future." (PMID 32636842, 2020). "Based on the evidence above, we hypothesize that PGE2 may affect IgE class switching, and contribute to asthma development through its regulation on PPARγ." (PMID 32636842, 2020).
asthma (continued). "However, PPARG and ESR1, as negative regulators, affect the transcription factor signaling pathway by inhibiting NF-κB, and some studies have found to support the potential benefits of PPARG agonists in the treatment of asthma." (PMID 32015750, 2020). "Distinct from PPARG, far less is known about ETV4 (ETS variant 4) in the context of asthma." (PMID 31506535, 2019). "Then, we hypothesized that these effects of curcumin in asthma would result from modulation of PPARγ." (PMID 31073274, 2019). "Some studies also support the potential benefits of PPARγ agonists in the treatment of asthma." (PMID 31073274, 2019). "PPARγ agonists also have direct effects on the airway in asthma." (PMID 26610598, 2015). "Indeed, a recent clinical trial found that rosiglitazone improved lung function in steroid-resistant asthma patients, providing direct evidence that patients with chronic airway inflammatory diseases can benefit from PPARγ agonist treatment." (PMID 22761606, 2012). "However, there is experimental evidence that methylation of H3/H4 results in down-regulation of PPARγ expression, mechanistically linking the epigenetic effect of nicotine with decreased lipofibroblast expression and asthma." (PMID 23106849, 2012). "It has been suggested that downregulation of PPARγ signaling may be a contributing factor to the development of AHR in asthma following in utero nicotine exposure, while the expression of PPARγ in ASM is upregulated in the airways of asthmatic patients." (PMID 22966222, 2012). "A proof of concept study using the PPARγ agonist rosiglitazone, demonstrated bronchodilator effects in mild to moderate smokers with asthma and further clinical trials of oral PPARγ agonists are underway in severe asthma." (PMID 21896202, 2011). "Accordingly, these results suggest that the therapeutic effect of PPARγ agonist in asthma is exerted by the down-regulation of IL-17 expression, providing a piece of evidence for an interaction between PPARγ signaling and IL-17 expression in allergic airway inflammation." (PMID 20565710, 2010). "The inhibitory effects of 15-d-PGJ2 were additive with fluticasone, offering the intriguing possibility that PPARγ agonists in combination with corticosteroids may provide additional therapeutic benefit in asthma." (PMID 18000530, 2007). "Adenoviral constructs expressing a dominant negative PPARγ gene that binds to the ligand and the PPRE on DNA but does not initiate transcription have been used in lung fibroblasts, while the effects of overexpression of functional PPARγ have been assessed in murine models of asthma." (PMID 18000530, 2007). "This suggests that oestrogen may promote the expression of PPARγ protein, which in turn may have a role in airway inflammation such as asthma and AR by affecting ILC2s, further revealing a new pathway of action of oestrogen in triggering asthma." (PMID 39800672, 2025). "Furthermore, PPARγ may represent a potential therapeutic target for interventions aimed at modulating senescence-associated processes in ACO.Key words ACO, Asthma, COPD, Macrophages, Senescence, PPARγ." (PMID 38643159, 2024). "PPARγ plays a role in regulating the Th2 imbalance and its mediated inflammation, and although a trial of pioglitazone in mild asthma failed, dietary modulation of PPARγ could improve or, alternatively, trigger inflammation in allergic reactions in the gastrointestinal system." (PMID 39451206, 2024). "Computational molecular docking of DCT compounds identified five proteins (ESR1, KDR, LTA4H, PDE4D and PPARG) mutually targeted by asthma genes and DCT compounds and 155 docking connections associated with cellular pathways involved in the biological mechanisms of asthma." (PMID 32185106, 2020). "Additionally, the studies confirmed that PPARγ, a ligand-activated transcription factor, plays a critical role in the mediation of inflammatory mediator release and inflammatory cell activation in asthma in both human and animals." (PMID 31073274, 2019).
asthma (continued). "Therefore, PPARγ activation by ligands could be also considered for the treatment of allergic diseases such as asthma." (PMID 27548145, 2016). "The use of substantially higher oral doses may not be associated with a positive benefit/risk profile in asthma since PPARγ agonists are associated with dose-related adverse effects such as weight gain (probably secondary to fluid retention)." (PMID 22966222, 2012). "Clinical evidence suggests that PPARγ and PPARγ ligands are involved in regulating inflammatory responses in the lung, and chronic or dysregulated inflammation is an important pathologic feature in many lung diseases including asthma, COPD, sarcoidosis, and pulmonary fibrosis." (PMID 22778711, 2012). "Therefore, androgens may precipitate asthma through a common genetic mechanism, since they, like nicotine, stimulate the Wnt pathway and down-regulate PPARγ expression in lung fibroblasts." (PMID 23106849, 2012). "It is critical to extend these comparisons to cells derived from asthmatics where the ability of corticosteroids to inhibit proliferation is reduced to determine whether PPARγ provides an additional or alternative therapeutic target to glucocorticoid receptors to regulate remodelling in asthma." (PMID 18000530, 2007). "For example, in a mouse model of asthma induced by ovalbumin (OVA) inhalation, PPARγ agonists such as rosiglitazone and pioglitazone reduced the increases in IL-17 mRNA and protein expression, airway inflammation, and bronchial hyperresponsiveness." (PMID 38360670, 2024). "Pharmacologic inhibition or genetic deletion of PPARγ in ILC2s abolished IL33-induced Th2 cytokine production and tumor growth in vivo, suggesting PPARγ inhibition as a target for ILC2-driven diseases beyond cancer (e.g., asthma, allergy)." (PMID 37686465, 2023). "Consequently, PPARG may be a therapeutic target for obese asthma." (PMID 36105239, 2022). "This has been further reinforced by studies showing significant co-expression of PPARG and IL9R in two independent asthma cohorts." (PMID 34697644, 2021). "PPARG is involved and acts downstream from the secondary KEGG asthma disease pathway PI3K-Akt signaling pathway through the AMP-activated protein kinase (AMPK) signaling pathway, to inhibit cell growth, cell survival and protein synthesis (KEGG)." (PMID 32185106, 2020). "The five identified target proteins, ESR1, KDR, LTA4H, PDE4D and PPARG, show evidence of involvement in the pathological expression of asthma, with three classified as receptors (ESR1, KDR, PPARG), and two categorized as enzymes (LTA4H, PDE4D) (KEGG, UniProt)." (PMID 32185106, 2020). "In brief, these data suggest that EP4 further regulates the expression of PPARγ by activating Akt and then PPARγ participates in the down-regulation of phospho-STAT6 and IgE production, eventually attenuating the development of asthma." (PMID 32636842, 2020). "Application of NeTFactor to a cohort of asthmatics and controls indicated that PPARG and ETV4 were the most likely regulators of an asthma biomarker." (PMID 31506535, 2019). "Ligands for PPARγ are negative regulators of effector T cell responses that ameliorate autoimmune or allergic diseases, including GVHD, EAE, and asthma." (PMID 27548145, 2016). "Several studies have examined the involvement of PPARγ and its ligand on AMH in a mouse model of asthma." (PMID 22761606, 2012). "However, whether the perinatal nicotine-induced asthma risk is restricted to nicotine-exposed offspring only; whether it can be transmitted to the next generation; and whether PPARγ agonists would have any effect on this process are not known." (PMID 23106849, 2012). "used Bergenin, a PPARγ agonist, to block the differentiation of naive CD4+ T cells into Th17 cells by inhibiting GLS1-dependent glutaminolysis under Th17-polarizing condition, thus alleviating asthma in mouse model." (PMID 37545506, 2023).